FOXP3 (forkhead box P3)
Diseases named in the same sentence as FOXP3 in open-access papers (continued):
Sharing a sentence is not in itself a finding about the gene and the disease.
breast carcinoma (continued). "Despite the limitations of our study, our meta-analysis is the first study to demonstrate the correlation between FOXP3+ TILs and the clinicopathological characteristics and prognosis in breast cancer." (PMID 26475790, 2015). "This meta-analysis indicates that a prognostic role for FOXP3 expression in operable breast cancer cases depends on the FOXP3-positive region, ER status, geographic region and the FOXP3-positive cut-off value." (PMID 26305693, 2015). "Recent studies have shown that the forkhead box P3 (FOXP3) protein has a prognostic role in breast cancer." (PMID 26305693, 2015). "Most of the included studies reported that FOXP3+ TILs was an indicator of poor prognosis applied unstratified breast cancer." (PMID 26475790, 2015). "The transcription factor Forkhead box P3 (FOXP3) which also positively regulates miR-7 expression in breast cancer has been found to have potential binding regions in the locality of MIR7-1 and MIR7-2 genes." (PMID 26308064, 2015). "So far, very few studies have been powered to evaluate if FOXP3+ TILs influence clinical outcomes in different breast cancer molecular subtypes." (PMID 26475790, 2015). "Lck can also phosphorylate FOXP3 at Tyr342 in breast cancer cells and increase FOXP3 transcriptional repression of mmp9, skp, and vegfa, and thus suppresses cellular invasion." (PMID 26441996, 2015). "Eligible studies describing the use of FOXP3 as a prognostic factor for operable breast cancer cases were identified." (PMID 26305693, 2015). "Of note, in addition to the well characterized role in a subset of regulatory T-cells, FOXP3 was reported to be functional also in mammary epithelial cells as a breast cancer suppressor gene." (PMID 24725474, 2014). "We then evaluated the prognostic effect of the interaction of FOXP3+ iTILs with CD8+ cytotoxic T-cell infiltrates in ER + breast cancers by building multivariate Cox regression models stratified by CD8+ iTIL status." (PMID 25193543, 2014). "To date, few studies have had sufficient power to investigate the prognostic effect of the interaction of FOXP3+ TILs with molecular subtypes or different types of immune response in breast cancer." (PMID 25193543, 2014). "To assess the prognostic value of FOXP3+ iTILs in the whole study cohort, we built Cox proportional hazards regression models to estimate the hazard ratio of FOXP3+ iTIL for breast cancer specific survival." (PMID 25193543, 2014). "FOXP3+ regulatory TILs are a poor prognostic indicator in ER+ breast cancer, but a favorable prognostic factor in the HER2+/ER+ subtype." (PMID 25193543, 2014). "In HER2+/ER– breast cancer, the multivariate analysis indicates that high FOXP3+ lymphocyte infiltration is a significant, independent and favorable prognostic factor in patients having tumors with CD8+ T-cell infiltrates." (PMID 25193543, 2014). "The prognostic significance of FOXP3+ tumor-infiltrating lymphocytes (TILs) in breast cancer, however, remains controversial." (PMID 25193543, 2014). "Recent data have further shown that γδ T cells from tumor tissues are positively correlated with Foxp3+ suppressive T cells in advanced breast tumors and inversely correlated with relapse-free and overall survival of breast cancer patients." (PMID 24741609, 2014). "One possible explanation consistent with these findings is that FOXP3+ TILs reflect tumor-induced immune evasion in ER + breast cancers." (PMID 25193543, 2014). "We evaluated the prognostic effect of FOXP3+ TILs in breast cancer, using a large population-based breast cancer cohort with long clinical follow-up." (PMID 25193543, 2014). "The multivariate analysis from our study confirms that, in ER + breast cancer, FOXP3+ regulatory TILs are an indicator for poor survival, at least in those tumors lacking concurrent cytotoxic CD8+ T-cell infiltration." (PMID 25193543, 2014).
breast carcinoma (continued). "The expression patterns of FOXP3 were examined by immunohistochemistry in primary breast cancer specimens from patients enrolled in the Milan 1 and Milan 3 trials." (PMID 25331657, 2014). "Some studies have applied ratios of CD8+: FOXP3+ TILs to evaluate the prognostic effect of immune response in breast cancer, and reported that those with a ratio of CD8+: FOXP3+ TILs ≥1 had better survival than those with ratios <1." (PMID 25193543, 2014). "The prognostic value of FOXP3+ TILs in breast cancer differs depending on ER and HER2 expression status and CD8+ T-cell infiltration." (PMID 25193543, 2014). "We immunohistochemically investigated the presence of B7-H3 and forkhead box P3 (Foxp3)-positive Tregs in pathological specimens from 90 patients with breast cancer." (PMID 24562936, 2014). "In our study, FOXP3+ TILs were found to be a favorable indicator of survival in ER– breast cancer, which is also consistent with the findings from other recently published studies." (PMID 25193543, 2014). "We analyzed pre- and post-treatment tumor-infiltrating immune cells (CD3, CD4, CD8, CD20, CD68, Foxp3) by immunohistochemistry in a series of 121 breast cancer patients homogeneously treated with neoadjuvant chemotherapy." (PMID 25432519, 2014). "We report herein for the first time that FOXP3 is expressed in cell line models of inflammatory breast cancer, an aggressive subtype of breast cancer with the worst survival outcomes." (PMID 23341929, 2013). "The present study has demonstrated that FOXP3 localization in breast cancer was crucial to predicting clinical outcome." (PMID 24649219, 2013). "The present study immunohistochemically investigated the prognostic relevance of FOXP3 expression in tumor cells and tumor-infiltrating lymphocytes (TILs) in breast cancer patients." (PMID 24649219, 2013). "Recent reports reveal that FOXP3 expression appears widespread in normal epithelia and aberrant in various solid tumors including breast cancer, ovarian cancer, prostate cancer, and pancreatic carcinoma and cells lines of colon cancer." (PMID 24155921, 2013). "It has been reported that dense intratumoral infiltration of Foxp3 +Tregs (Tregs) was an independent factor for poor prognosis of breast cancer (BC) patients." (PMID 24124553, 2013). "Increased levels of FoxP3-positive Tregs in peripheral blood and tumor have been reported in patients with various types of cancer including ovarian cancer, breast cancer and other tumors." (PMID 23537231, 2013). "By contrast, previous immunohistochemical studies indicated that FOXP3 cytoplasmic expression was more abundant, compared to nuclear expression, in several types of cancer, including breast carcinoma." (PMID 24649219, 2013). "Specifically in breast carcinoma, the number of FOXP3 CD4+CD25+ Treg and decreased ratios of CD8 T cells/FOXP3 Treg are correlated with a poor prognosis." (PMID 23861693, 2013). "Two previously conducted representative immunohistological studies demonstrated that FOXP3 staining of breast cancer specimens was localized either completely or predominantly in the tumor-cell cytoplasm, with only a few specimens exhibiting nuclear staining." (PMID 24649219, 2013). "A few studies have indicated that CCL22 secreted by solid tumor cells is responsible for accumulation of Foxp3 +Tregs in ovarian, prostate, gastric, esophageal, and breast carcinomas." (PMID 24124553, 2013). "In this study, immunohistochemistry was used to investigate the prognostic significance of FOXP3 expression in tumor cells and tumor-infiltrating lymphocytes (TILs) in breast cancer patients." (PMID 24649219, 2013). "FOXP3 is reported to be a mammary tumor suppressor and LCK is expressed in breast cancer tissues and cell lines." (PMID 24155921, 2013).
breast carcinoma (continued). "Higher total numbers of FOXP3+ (p = 0.026) lymphocytes were observed in small breast cancers (tumor size ≤ 2 cm; T1) with positive lymph nodes (N+), as compared with tumors of the same T1 stage without lymph node metastases (N0)." (PMID 22471961, 2012). "In our studies however, in keeping with previous results expression of FOXP3 in breast cancer cells was found to be negligible while it was usually detectable as nuclear staining of TIL." (PMID 22471961, 2012). "In our study, the Foxp3+ SIs in breast cancer PTs were significantly higher than those in benign diseases and normal adjacent tissues, but lower than those in the TDLNs which showed the same pattern as the IDO+SIs." (PMID 22110525, 2011). "The Foxp3+ SIs in breast cancer PTs were significantly higher than those of benign breast diseases and normal breast tissues, which were 3.50 ± 1.04%, 0.71 ± 0.42%, and 0.55 ± 0.34%, respectively, (P < 0.05)." (PMID 22110525, 2011). "In fact, high FoxP3 expression is associated with increased TGFβ and VEGF levels, invasiveness, and metastasis in infiltrating breast carcinoma, indicating that FoxP3 expression can be used as a prognostic indicator." (PMID 24281102, 2010). "We studied SLN in breast cancer patients and observed an accumulation of Foxp3+ cells in metastatic lymph nodes." (PMID 19604349, 2009). "Our results demonstrating Foxp3+ cell infiltration within metastatic SLN of breast cancer patients are in line with other studies that correlate high numbers of Tregs with a metastatic and invasive growth pattern of cancer." (PMID 19604349, 2009). "Sentinel lymph nodes (SLN) of 47 breast cancer patients with varying degrees of nodal disease and 10 controls were evaluated for expression of Foxp3 and IDO using immunohistochemistry." (PMID 19604349, 2009). "In tumor-free SLN of breast cancer patients and in controls a correlation between Foxp3+ and IDO+ cells was observed." (PMID 19604349, 2009). "Using immunohistochemistry, tumor sections from 62 breast cancer patients were co-stained for B7-H1, PD-1 and FOXP3 molecules and their expression was statistically correlated with factors known to be involved in the progression of the disease." (PMID 18294387, 2008). "We examined the association between tumor expression of Globo H and the presence of Treg cells as detected by forkhead box protein P3 (FOXP3) expression in clinical specimens from 73 patients with breast cancer (BC) and 85 patients with hepatocellular carcinomas (HCC)." (PMID 40532063, 2025). "A single-cell RNA-seq analysis comparing primary and metastatic ER+ breast cancers revealed an enrichment of chemokine ligand 2-positive (CCL2+; encoded by CCL2) tumor-associated macrophages, FOXP3+ regulatory T cells, and exhausted CD8+ T cells in metastatic lesions." (PMID 41550427, 2025). "Importantly, these results were validated in the GEO dataset, where elevated CD8a/FOXP3 was predictive of improved survival in ER– breast cancer patients." (PMID 40663402, 2025). "Future studies incorporating multiplexing to identify functional subsets of FOXP3+ Tregs may inform prognosis and predictive relevance of T regulatory cells in the context of adjuvant radiation therapy in breast cancer." (PMID 40883317, 2025). "The role of FOXP3(+) regulatory cells in breast carcinoma has been largely appreciated." (PMID 40243442, 2025). "In addition, Gal-1 regulates the anti-tumor properties of Foxp3 by binding with the FKH domain of Foxp3 in Foxp3-positive breast cancer cells, thereby maintaining the stability of cancer cells." (PMID 38919615, 2024). "RANKL is derived from CD4+ FOXP3+ T cells in breast cancer and arthritis." (PMID 38902257, 2024). "Moreover, FOXP3 expression has been confirmed in both healthy breast cancer tissue as well as breast cancer cells." (PMID 38637568, 2024). "The presence of regulatory T lymphocytes (Tregs), specifically the Foxp3 expressing subtype, is associated with a negative prognosis in breast cancer patients." (PMID 38533507, 2024).
breast carcinoma (continued). "Additionally, FOXP3 is an independent prognostic factor in breast cancer, with high expression levels indicating a poor prognosis in late-stage patients." (PMID 39668835, 2024). "This research not only offers preclinical evidence that supports the use of ADQ to inhibit lung metastasis in breast cancer but also reveals new perspectives on the TAM/CXCL1/NF-κB/FOXP3 signaling pathway as a viable target for Treg modulation and the immunotherapy of breast cancer." (PMID 39090094, 2024). "Additionally, FoxP3 is expressed in the nucleus in these cancers, whereas it is more abundant in the cytoplasm in some cancers such as breast cancer and pancreatic cancer." (PMID 39150932, 2024). "UBC9 is the only E2 enzyme for Small Ubiquitin-like Modifier (SUMO), which can also target the UBC9 promoter region to up-regulate SUMOization to regulate Foxp3+ Treg cell function after phosphorylation modification of the Y342F site of Foxp3 in human breast cancer cells." (PMID 38919615, 2024). "FOXP3 expression as a new independent prognostic factor in breast carcinoma, which might help to improve the selection of patients for appropriate therapy." (PMID 39664195, 2024). "Furthermore, FOXP3 inhibits oncogenic ErbB2 overexpression by binding to the ErbB2 promoter, which ultimately inhibits breast cancer progression." (PMID 39668835, 2024). "The high incidence of somatic mutations contributed to the absence of FOXP3 or the abnormal expression of short FOXP3 splicing isoforms in breast cancer cells, leading to the impairment in HER2 oncogene suppression." (PMID 37868998, 2023). "FoxP3 deletion leads to spontaneous breast cancer, and chromosome inactivation may lead to the inactivation of the normal FoxP3 gene in mice with heterozygous mutations." (PMID 37834313, 2023). "The TME of intracranial breast cancer lesions exhibits significant immunosuppressive characteristics, characterized by the presence of FOXP3 + regulatory T cells (Tregs), LAMP3 + dendritic cells, CCL18 + M2 macrophages, RGS5 + tumor-related fibroblasts and LGALS1 + microglia." (PMID 38104104, 2023). "Other authors have reported that both peritumoural CD8+ and FOXP3+ lymphocytic infiltrates are associated with a good outcome, mainly in receptor-negative early breast cancer." (PMID 38273853, 2023). "In breast cancer patients receiving mastectomy, initially on post-op day 1, a significant decrease in FOXP3 mRNA in the peripheral blood could be detected." (PMID 37568571, 2023). "Several studies have reported the FOXP3 expression increase in tumor cells, and in some cases with tumor suppressor activity, as in ovarian, prostate, and breast cancer, but also as an oncoprotein, as in gastric, bladder, lung, and cervical cancer, among others." (PMID 36672296, 2023). "For this reason, we can conclude that the association of a higher number of Foxp3+ cells with the lack of ER expression is a further clue of the negative prognostic value of T regs in canine mammary carcinoma." (PMID 36766393, 2023). "Our findings confirm that the number of Tregs is significantly higher in canine mammary carcinomas than adenomas and that a high number of Foxp3+ cells were associated with negative prognostic factors and shorter overall survival (OS)." (PMID 36766393, 2023). "It remains open as to whether TIL subtypes linked with presumably protumor characteristics, such as PD-1+ TILs and FOXP3+ TILs, are linked with a higher or lower response to chemotherapeutics used in the NST of breast cancer." (PMID 37835488, 2023). "Although Foxp3 expression within the immune system is virtually restricted to Tregs, this transcription factor has also been detected in several types of normal and tumoral epithelial cells, including breast cancer (BRCA) cells." (PMID 37766222, 2023).
breast carcinoma (continued). "In addition, the studies show that CAF-S1 subtype, which have high Alpha SMA and FAP positivity have clearly demonstrated an immunosuppressive function in breast cancer and attract FOXP3 regulatory T-cells." (PMID 38192631, 2023). "Our results suggest that Foxp3 exerts protumoral intrinsic effects in breast cancer cells and that gene-therapy-mediated blockade of Foxp3 could constitute a therapeutic strategy to improve the response of these tumors to standard treatment." (PMID 37766222, 2023). "In breast cancer, FoxP3 could induce the transcriptional activity of miR-200c and miR-141, which were elevated in patients with metastatic breast cancer." (PMID 37569676, 2023). "Furthermore, the mean value of Foxp3+ lymphocytes was related to immunohistochemical features of mammary carcinoma, particularly the expression of hormones and C-erbB-2 receptors." (PMID 36766393, 2023). "Therapeutic blocking of Tregs-specific FOXP3 reduced breast cancer growth in animal models." (PMID 37868998, 2023). "Dormant mammary tumors have high levels of infiltrating FoxP3+ Treg cells." (PMID 37847565, 2023). "FOXP3 also inhibited growth and induced the cell death of a breast cancer cell line MCF-742." (PMID 35614183, 2022). "The prognostic value of Tregs in the context of IHC FOXP3 positivity or suppressive function of FOXP3+ TILs in breast cancer remains unclear." (PMID 35565267, 2022). "Finally, we found that FOXP3 expression predicted the breast cancer cells response to anticancer drugs." (PMID 35614183, 2022). "Metaplastic breast cancer, which was also reported as poorly responsive to neoadjuvant treatment, frequently expresses immune checkpoint markers forkhead box P3 (FOXP3) and PD-L1 and may benefit from immune-based therapies." (PMID 35163586, 2022). "CD4 + /Foxp3 + cells are Tregs, and CD4-/Foxp3 + cells might be E0771 breast cancer cells expressing Foxp3." (PMID 36316775, 2022). "For one thing, FOXP3 is a tumor suppressor of breast cancer and prostate cancer." (PMID 35401877, 2022). "We wanted to see if this phenomenon was true in the in vivo animal model because both breast cancer patient-derived Tregs and ex vivo-generated Treg cells showed a dependency of FOXP3 in the transcriptional regulation of CCR4, the key regulator of Treg infiltration in the TME." (PMID 35222362, 2022). "Additionally, FOXP3 has a significant positive correlation with PDCD1, CD274, CTLA4 and TMB in breast cancer, and FOXP3 expression showed a statistically significant correlation with infiltration of immune cells." (PMID 35614183, 2022). "Also, reactivation of endogenous FOXP3 in breast cancer cells by CRISPRi/a inhibited tumor growth in vitro and in vivo." (PMID 35130925, 2022). "Moreover, we provide data to show poor clinical outcomes in breast cancer patients with exceedingly high CD8+ TC/IM ratios, which were associated with increased frequencies of CD163+ and FoxP3+ cells." (PMID 36551693, 2022). "In addition, Some studies have demonstrated that FOXP3 is an important tumor suppressor of oncogenes in breast cancer with good prognosis." (PMID 35614183, 2022). "The prognostic value of FOXP3+ TILs in breast cancer outcomes remains controversial." (PMID 35565267, 2022). "Moreover, the I-309/CCL1 was highly expressed in human breast cancer; in addition, the high expression of this chemokine correlated with the infiltration of immunosuppressive FoxP3+ Tregs, which negatively affect patient survival." (PMID 36354566, 2022). "FOXP3 directly restrains CD44 breast cancer by participating in the corresponding regulatory role." (PMID 36160018, 2022). "Notably, increasing expression of Tregs regulator forkhead box protein 3 (FOXP3) is identified in many tumors such as breast cancer, melanoma, and pancreatic cancer with a complicated function and cell type-related manner." (PMID 33968014, 2021).